VPREB1 (V-set pre-B cell surrogate light chain 1)
Description:
Associates with the Ig-mu chain to form a molecular complex that is expressed on the surface of pre-B-cells. This complex presumably regulates Ig gene rearrangements in the early steps of B-cell differentiation.
Synonyms: CD179a; VPREB; IGI; IGVPB
Tractability: Antibody: its Gene Ontology location is reachable by antibodies, with high confidence; UniProt predicts a signal peptide or a membrane-spanning region.
Gene: Protein-coding gene on chromosome 22 (22,244,780 to 22,245,515, forward strand). Ensembl gene ENSG00000169575.
Subcellular location: Endoplasmic reticulum
Pathways (Reactome):
Hemostasis: Cell surface interactions at the vascular wall
Gene Ontology:
Biological process: immune response
Cellular component: endoplasmic reticulum; extracellular region; immunoglobulin complex
Genetic constraint (gnomAD): Loss-of-function variants: 17 observed, 12.78 expected, observed/expected ratio (o/e) 1.33, 90% interval 0.9 to 1.86. The upper end of that interval is the gene's LOEUF score, 1.86, which puts it in group 6 of 6, group 1 being the genes least tolerant of losing a copy. Missense variants: 183 observed, 181.95 expected, observed/expected ratio (o/e) 1.01, 90% interval 0.89 to 1.14. Synonymous variants: 86 observed, 73.78 expected, observed/expected ratio (o/e) 1.17, 90% interval 0.98 to 1.39.
Homologues: Orthologues: chimpanzee VPREB1 (98% identical), macaque VPREB1 (92% identical), mouse Vpreb1a (71% identical), mouse Vpreb1b (71% identical), guinea pig VPREB1 (68% identical), rat Vpreb1b (66% identical), rat Vpreb1a (66% identical), pig VPREB1 (64% identical), rabbit VPREB2 (64% identical), dog VPREB1 (63% identical). Paralogues in human: IGLV5-37 (46% identical), IGLV5-52 (42% identical), IGLV5-45 (41% identical), IGLV11-55 (40% identical), IGLV1-40 (38% identical), IGLV4-60 (38% identical), IGLV1-50 (37% identical), IGLV5-48 (37% identical), IGLV6-57 (37% identical), IGLV1-47 (36% identical), IGLV2-14 (36% identical), IGLV2-18 (36% identical), and 81 more.
Diseases named in the same sentence as VPREB1 in open-access papers:
VPREB1 is named in the same sentence as 15 diseases in open-access papers, as found by Europe PMC text mining. Sharing a sentence is not in itself a finding about the gene and the disease. The quoted sentences say what the papers report.
B cell lymphoma (2 papers, 2008 to 2021). "First, expression of VpreB1 and λ5 from the λ5-IRES-VpreB1-EGFP retroviral vector was demonstrated by transducing the immature B cell lymphoma WEHI231 and staining for surface expression of total pre-BCR or λ5." (PMID 18974788, 2008).
leukemia (2 papers, 2016). A malignant (clonal) hematologic disorder, involving hematopoietic stem cells and characterized by the presence of primitive or atypical myeloid or lymphoid cells in the bone marrow and the blood. "The authors postulate that deletions of the following genes ETV6, VPREB1, CDKN2A/B, TBL1XR1, PAX5 as well as BTLA and CD200 are very early and essential events in leukemia development." (PMID 27933341, 2016).
myeloma (2 papers, 2021). "Accordingly, we hypothesized that if we are able to in-vitro knock-out the VPREB1 gene in myeloma cells using specific guide RNA sequence linked to CRISPR/Cas9 nuclease, the VPREB1 protein expression is reduced and therefore we can inhibit the proliferation of human myeloma cells." (PMID 33418558, 2021). "Based on bioinformatics analysis, we identified that VPREB1 protein is overexpressed in multiple myeloma as well as other B cell malignancies." (PMID 33418558, 2021). "Two CRISPR/Cas9 mediated approaches for the knock-out of VPREB1 gene in primary human myeloma cells were used in this study." (PMID 33418558, 2021). "CRISPR-cas9-mediated knock-out of VPREB1 gene is effective for inhibiting the proliferation of primary myeloma cells." (PMID 33418558, 2021). "Based on our results, knock-out of VPREB1 gene showed significant reduction at both VPREB1 mRNA and protein expression levels in treated human myeloma cells, verifying the efficiency of knock out procedure." (PMID 33418558, 2021). "We aimed to knock-out the human VPREB1 gene in primary myeloma cell line using CRISPR/Cas9 gene editing technology." (PMID 33418558, 2021). "The VPREB1 gene knock-out by both approaches were more powerful to suppress cell proliferation and impair viability when compared to the untreated myeloma cells." (PMID 33418558, 2021). "The VPREB1 gene expression was decreased in edited myeloma cells as compared to un-edited cells (p<0.01), indicating that transfection and editing were successful." (PMID 33418558, 2021). "knock-out of VPREB1 gene in myeloma cell line resulted in a statistically significant reduction of myeloma cell proliferation." (PMID 33418558, 2021). "CRISPR-Cas9–mediated knockout of VPREB1 on primary MM cells was done, and it resulted in reduction of myeloma cell proliferation." (PMID 35154242, 2021). "We aimed to investigate the in-vitro effect of CRISPR-cas9-mediated knock-out of V-set pre B-cell surrogate light chain 1”VPREB1” gene on the malignant proliferation of primary cultured myeloma cells." (PMID 33418558, 2021). "An immunofluorescent staining was performed on cultured myeloma cells to detect the VPREB1 protein expression in edited vs un-edited cells." (PMID 33418558, 2021). "Although, lower expression level of the VPREB1 protein was observed in myeloma cells that were edited by the 1st approach as compared to that of 2nd approach, this was statistically insignificant (p>0.05)." (PMID 33418558, 2021). "Our results revealed that VPREB1 edited myeloma cells showed lower cell count compared to the untreated myeloma cells." (PMID 33418558, 2021). "In addition, large-scale study should be designed to address different pathways that are involved in the proliferation inhibition of myeloma cells by VPREB1 gene knock-out." (PMID 33418558, 2021). "In conclusion, we are successful to validate our hypothesis that CRISPR/Cas9-mediated knock- out of VPREB1 gene in myeloma cells efficiently inhibits their proliferation." (PMID 33418558, 2021). "In addition, VPREB1 gene editing had a proliferation inhibition effect on myeloma cells." (PMID 33418558, 2021). "We knocked-out the VPREB1 gene in primary cultured myeloma cells using CRISPR-cas9, the VPREB1 gene editing efficacy was verified by determining VPREB1 gene expression at both the mRNA and protein levels by qPCR and immunofluorescence, respectively." (PMID 33418558, 2021).
rheumatoid arthritis (1 paper, 2020). A chronic, systemic autoimmune disorder characterized by inflammation in the synovial membranes and articular surfaces. "B cells are important components of rheumatoid arthritis- (RA-) mediated immune response; hence, CNV in the regulators of B cells (such as VPREB1) can influence RA susceptibility." (PMID 33101545, 2020).
VPREB1 also shares sentences with these, for which no sentence is quoted: acute lymphoblastic leukemia (1 paper); astrocytoma (1); cancer (1); chronic lymphocytic leukemia (1); Ewing sarcoma (1); multiple myeloma (1); myeloid tumors (1); pediatric tumors (1); precursor T-cell lymphoblastic lymphoma (1); primary immunodeficiency (1); tumor (1).